MUC1 (mucin 1, cell surface associated)
Diseases named in the same sentence as MUC1 in open-access papers (continued):
Sharing a sentence is not in itself a finding about the gene and the disease.
tumor (continued). "In this review, we will cover the binding specificities of Siglecs to TA MUC1 and the functional role these interactions play in the modulation of the tumor immune microenvironment." (PMID 38611013, 2024). "Although MUC1 gene overexpression is typical for both normal epithelium and epithelial tumor cells, its isoform Y is considered tumor-specific." (PMID 38966179, 2024). "The high expression of MUC1 in tumors makes it a potential tumor biomarker and therapeutic target, applied in the diagnosis and biological treatment of various cancers." (PMID 39491020, 2024). "Mucin-1 (MUC-1) is a type I transmembrane protein that promotes tumor invasion, angiogenesis, and metastasis." (PMID 38756774, 2024). "We carried out immunohistochemical staining of MUC1, CD56, and CD16 on tissue sections of the tumor, liver, lung, and spleen collected from a representative xenograft mouse in the iPSC-derived MUC1-targeted CAR-NK cells group." (PMID 38390321, 2024). "Carcinoembryonic antigen 15-3 (CA15-3), a member of the mucin-1 (MUC-1) glycoprotein family, is recognized as a valuable tumor marker." (PMID 39742378, 2024). "Fully human MUC1-specific antibodies were cloned from a vaccinated participant into an IgG1 backbone vector and evaluated for their ability to recognize MUC1 on tumor cells." (PMID 39449327, 2024). "We found that MUC1 knockdown increased PD‐L1 expression, indicating the high expression of MUC1 in tumour tissues leads to resistance to anti‐PD‐L1 immunotherapy." (PMID 38778448, 2024). "For example, oncolytic adenoviruses targeting both the MUC1 and hTERT promoters have shown enhanced tumor targeting and the ability to overcome tumor heterogeneity in preclinical models." (PMID 39886667, 2024). "These properties and the inclusion of multiple cell lines/tumor types should be considered in the design and future development of therapeutics for MUC1 and other key tumor targets." (PMID 39449327, 2024). "With the development of MCA, numerous MUC1 proteins were secreted by cancer cells and accumulated in the tumour microenvironment." (PMID 38778448, 2024). "GT-00AxIL-15 is an IL-15-based ICK targeting the tumor-specific, glycosylated epitope of MUC1 (TA-MUC1)." (PMID 39204319, 2024). "At the same time, Muc1 and Cldn7 expression was statistically significantly higher in the tumor tissue of the SH mice in comparison with the TH mice, which is likely associated with a more severe course of CAC." (PMID 39063041, 2024). "Tumour cell derived‐MUC1 can interact with nuclear factor‐kappa B (NF‐κB) to induce the expression of interleukin‐6 (IL‐6), an essential cytokine for fibroblast activation and migration." (PMID 38778448, 2024). "MUC1 acts as a dual role of tumor marker and immunotherapy target in GU cancers, although its specific functions are still challenging to define." (PMID 39491020, 2024). "Tumor recognition by MUC1, 5T4, and NCAM-specific CARs was more effective when the long spacer was used (longer/flexible)." (PMID 38178096, 2024). "When cells undergo malignant transformation, abnormal O-glycosylation leads to the conversion of the original O-glycan structures into Tn antigens, sialyl Tn antigens, or T antigens, making MUC1 a tumor antigen recognizable by the immune system." (PMID 39491020, 2024). "In tumor cells, heightened MUC1 expression, combined with reduced glycosylation and altered polar distribution, modifies interactions with cell surface receptors." (PMID 38361923, 2024). "Collectively, these findings and the demonstration that MUC1 associates with expression of ∆Np63, SOX2, and NOTCH3 in individual HNSCC tumor cells indicate that MUC1-C is a common effector of the HNSCC CSC state." (PMID 38619287, 2024). "A co‐infiltrated pattern between C1Q+ TAMs and MUC1+ tumour cells was discovered and found to be consistent in the external cohort." (PMID 39422697, 2024).
tumor (continued). "Together, our results illustrated the expression patterns of EGFR and MUC1 in tumor and normal tissues, and suggested that they were promising drug targets for developing cancer therapies targeting dual TAAs." (PMID 39664199, 2024). "We investigated the expression patterns of EGFR and MUC1 in patients with LUAD and CRC by IHC, and observed high expression of EGFR and MUC1 in tumor tissues." (PMID 39664199, 2024). "MUC1 expression partially increases tumor invasion and metastasis and promotes the creation of tumor blood vessels." (PMID 38540735, 2024). "CAR-T cells targeting the Tn and STn antigen on MUC1 have shown specific recognition on different tumor cells in vitro and displayed effective antitumor activity in murine models of cancers, including leukemia and pancreatic cancer." (PMID 38727261, 2024). "In ccRCC, MUC1 is known to be diffusely overexpressed, having correlations with tumor progression, nuclear grade, worsened outcome, and metastatic disease." (PMID 38254882, 2024). "Overall, our results support the potential use of Napabucasin as an efficacious anti-tumor therapeutic agent with a probability of better outcome in high-MUC1 tumor sub-populations, singly or in combination with other therapeutic agents." (PMID 38326371, 2024). "Intriguingly, the aberrant expression of specific MUC proteins, notably Mucin 1 (MUC1) and Mucin 16 (MUC16), within tumor cells, is intimately associated with oncogenesis, proliferation, and metastasis." (PMID 38361923, 2024). "Specifically, the MUC1 promoter demonstrates superior transcriptional activity in these MUC1-overexpressing tumor cells compared to the hTERT promoter." (PMID 39886667, 2024). "To further explore the crosstalk between MCA tumour cells and macrophages, we knocked down MUC1 in tumour cells and then co‐cultured with macrophages." (PMID 38778448, 2024). "In recent years, a number of therapeutic strategies targeting MUC1 have been developed and their value for tumor therapy have been demonstrated experimentally." (PMID 38164273, 2024). "Os níveis de CK20 e MUC1 podem ser avaliados por qRT-PCR a partir de amostras de sangue periférico total de pacientes com câncer gástrico, os níveis de CK20 estavam correlacionados com os de MUC1, assim como tamanho do tumor." (PMID 38324850, 2024). "Overall, our rAdF35-MUC1 exhibits enhanced selective replication and expression capabilities in tumor cells that overexpress MUC1." (PMID 39886667, 2024). "Co-administration of PSCA and MUC1 targeted CAR T cells showed a tumor-killing effect in an in vivo mice model implanted with NSCLC cells." (PMID 39835140, 2024). "The exposed Tn antigen is the ligand of Ca2+dependent C-type lectin receptor MGL (macrophage galactose type lectin/CD301/CLEC10A), MGL specifically recognizes tumor derived mucin MUC1 by binding to Tn antigen." (PMID 38699634, 2024). "Another microcantilever-based aptasensor was developed for the detection of the transmembrane epithelial tumor biomarker MUC1." (PMID 37175137, 2023). "Recently, it has been demonstrated that tandem repeats regions of MUC1 are able to activate NF-κB, a transcription factor implemented in pro-inflammatory responses, the induction of resistance to chemotherapy, tumor progression, invasion, and metastasis." (PMID 37345016, 2023). "In animal tumor models, the effective dosage of SAR566658 correlates with the expression of CA6, a MUC1-associated sialic acid glycoprotein." (PMID 37305567, 2023). "Taken together with the fact that tumor suppression was only seen when BMDCs were administered together with MUC1 DNA, it is reasonable to assume that a MUC1-specific acquired immune response is involved." (PMID 36980805, 2023). "Much of the evidence suggests that mast cells can promote tumor progression and angiogenesis; thus, we evaluated the infiltration of tryptase-positive cells in the tumor microenvironment according to MUC1 expression." (PMID 36902242, 2023).
tumor (continued). "To date, the most widely explored tumor antigens include mucin-1 (MUC-1), carcino-embryonic antigen (CEA), HER2, and cancer-testis antigens." (PMID 36992161, 2023). "Tumor cells overexpress MUC1, activating the intracellular pathways involved in cancer proliferation." (PMID 36900394, 2023). "Immunized MUC1 transgenic mice with the Qβ-MUC1 vaccine produced high levels of antibodies against MUC1, exhibiting tumor protection in metastasis and solid tumor models." (PMID 36851313, 2023). "The distinctive biological structure of MUC1 and its aberrant glycosylation in cancer cells make it a recognized tumor-specific antigen on epithelial tumor cells." (PMID 37654484, 2023). "MUC1, over-expressed in the cancer state, stimulates tumor cell release from initial tumor sites by suppressing E-cadherin-mediated cell-cell and integrin-mediated cancer-extracellular matrix interactions, promoting metastasis." (PMID 37345016, 2023). "One of the glycoproteins, which undergoes specific alterations in the glycosylation of tumor cells is epithelial MUC1 mucin, which is highly overexpressed in the malignant state." (PMID 37345016, 2023). "Although the upregulation of MUC1 in the primary tumour correlates with metastatic recurrence after surgical resection (p < 0.01), there has been little research into the use of MUC1 expression alone in the diagnosis of OSqCc." (PMID 37958425, 2023). "The study found secretion of IL-22 induced the expression of MUC1 on tumour cells allowing CAR-T cells to bind more accurately." (PMID 39935547, 2023). "Mucin1 (MUC1) is abnormally glycosylated and overexpressed in a variety of epithelial cancers and plays a critical role in tumor progression." (PMID 37489369, 2023). "Depolarized MUC1 expression was related to the presence of lymphatic invasion, tumor diameter, and stage." (PMID 36367122, 2023). "The abnormal glycosylation of MUC1 will lead to the formation of tumor-related antigen epitopes (new protein or carbohydrate epitopes)." (PMID 37489369, 2023). "This BsAb was designed in an asymmetric Fab-ScFv-IgG format with a Fab arm binding to MUC1 on tumor cells and a ScFv arm recognizing CD3 on T cells." (PMID 37489369, 2023). "The combination of MUC1 DNA and BMDCs reduced the tumor burden more than in the controls, showing an additive preventive effect." (PMID 36980805, 2023). "In vitro, downregulation of MUC-1 was associated with AKT and ERK suppression, decreased VEGF and VEGF-C, tumor cell proliferation inhibition and increased cell apoptosis in NSCLC." (PMID 36895477, 2023). "Tecemotide (L-BLP25) is a MUC1 antigen-specific tumor vaccine to induce T cell immunity against MUC1." (PMID 36895477, 2023). "In humans, injection of oxidized mannan-MUC1 after breast cancer surgery successfully prevented tumor recurrence for up to 15 years." (PMID 36980805, 2023). "Since adenocarcinomas are heterogeneous, how should we evaluate MUC1 staining within different patterns of the same tumor?" (PMID 36367122, 2023). "A MUC1-targeted dendritic-cell-based vaccine exhibited anti-tumor activity and clinical benefits for patients with MUC1-positive refractory NSCLC." (PMID 36895477, 2023). "MUC1 can regulate tumor progression through a variety of mechanisms, including immune response, tumor invasion, tumor cell proliferation and apoptosis, and angiogenesis." (PMID 36738352, 2023). "Immunostaining for CA 19-9 and MUC1 showed a significantly higher expression in the neoplastic tissue compared to non-tumor ductal and acinar tissues (p < 0.001)." (PMID 37760554, 2023). "In tumors, MUC1 is more involved in different signaling pathways that influence and regulate tumor growth, survival, invasion, migration, and apoptosis." (PMID 37608294, 2023). "But MUC1 alters and regulates different signaling mechanism to inhibit the apoptosis process and lead to tumor development, tumor progression and drug resistance." (PMID 37650011, 2023).
tumor (continued). "Tumor markers (MUC1, EGFR, and EPCAM) are identified in CCA, and this marker combination is applied to detect tEVs in clinical bile samples." (PMID 36698298, 2023). "MUC1 has received remark attention as an oncogenic molecule and is considered a valuable tumor target for immunotherapy, while many monoclonal antibodies (mAbs) targeting MUC1-positive cancers in clinical studies lack satisfactory results." (PMID 37489369, 2023). "Intensified resistance against immunosuppressive cytokines as well as heightened anti-tumor efficacy is the manifested traits of MUC1-CAR T-cells engineered with IL-4 receptor ectodomain." (PMID 37020537, 2023). "MCF-7 tumor cells overexpressing MUC1 on their surface were used as a model target; aptamer-cell complexing and subsequent mass loading led to a phase shift, and a LOD as low as 32 cells/mL was achieved for MCF-7 cells." (PMID 37175137, 2023). "Silencing of MUC1 also enhanced the anti-tumor efficacy of paclitaxel against paclitaxel-resistant cell line A549/PR in NSCLC via Bax and Caspase-3 upregulation and Bcl-2 downregulation." (PMID 36895477, 2023). "When lectin (Siglec-9) binds to the ST structure on MUC1 of myeloma cells, it promotes the formation of the tumor microenvironment (TME) and thus metastasis." (PMID 37894512, 2023). "A nanovaccine that comprises certain tumor antigens like carcinoembryonic antigen (CEA) or mucin 1 (MUC1) that demonstrates a response resistance to sickness and tumor progression has demonstrated promising outcomes in clinical models." (PMID 37427139, 2023). "In vivo experiments, the average tumor volumes for Gem NPs, MUC1 inhibitor NPs, Gem-MUC1 inhibitor NPs, blank NPs, 5-FU, and sterile saline were approximately 828.75, 747.07, 473.75, 1055.14, 373.92, and 1119 mm3, respectively." (PMID 38026861, 2023). "Owing to its aberrant glycosylation, tumour-specific CAR T-cells targeted against MUC1 have been described by a number of groups." (PMID 36829563, 2023). "The cells were transfected with adenovirus type 5 (Ad5) vectors containing mRNA molecules encoding for three fixed tumor antigens: suppressor of cytokine signaling (SOCS) 1, MUC1, and survivin." (PMID 38067293, 2023). "The adhesion molecules on the surface of CTCs, such as CD44 and MUC1, can bind to selectins so that the weak adhesion between tumor cells and the endothelium is established." (PMID 37108248, 2023). "The treatment of PCa cell lines and their xenografts in nude mice with MUC1 inhibitor decreased tumor progression and recurrence." (PMID 36980526, 2023). "Consistent with the in vitro cytotoxicity assay, MUC1/CD3 BsAb treatment can significantly inhibit MUC1-positive tumor cell growth in the xenograft mouse model." (PMID 37489369, 2023). "For instance, MUC1 is highly expressed in over 60% of PC patients and is negatively correlated with tumor size and patient prognosis." (PMID 37304241, 2023). "MUC-1 expression on tumor cells promotes metastasis by binding to intercellular adhesion molecule-1 (ICAM-1) in endothelial cells." (PMID 36895477, 2023). "The National Cancer Institute Translational Research Working Group has listed MUC1 as the second promising target in cancer research from 75 tumor-related antigens." (PMID 37654484, 2023). "Our MUC1/CD3 BsAb can efficiently redirect T cells to kill MUC1-positive tumor cells in vitro and in vivo." (PMID 37489369, 2023). "What mechanisms mediate the effect of tumor prevention by vaccination with MUC1 + BMDCs in the AOM-DSS-induced colorectal carcinogenesis model remains to be elucidated." (PMID 36980805, 2023). "Therefore, higher levels of galectins in sera from cancer patients and increased expression of MUC1 and TF antigen-associated MUC1 by cancer cells might enhance molecular interactions between circulating galectins and TF/MUC1, promoting tumor cell adhesion to vascular endothelium and metastasis." (PMID 37898403, 2023).
tumor (continued). "In cancer, overexpression of MUC1 interferes with cell adhesion, protects tumor cells from immune recognition, and promotes metastasis." (PMID 37110670, 2023). "When the stigmergy was evaluated between the two nanoparticles using in vivo imaging the first nanoparticle conjugated with the MUC1 aptamer showed maximum localization to the tumor." (PMID 37149607, 2023). "Previously, we have shown that the growth of administered MUC1-expressing tumor cells in MUC1.Tg mice is enhanced, likely due to the presence of MUC1-specific regulatory T cells." (PMID 36980805, 2023). "Examples of TAAs include MUC1, which is abnormally overexpressed in many tumor cells, as well as gp100 and MART1, which are respectively overexpressed and abnormally expressed in most melanoma cancer cells." (PMID 37936701, 2023). "MUC1, the first mucin identified, has been found in tumor cells to exhibit upregulated expression, abnormal glycosylation, and nonpolar distribution." (PMID 37664708, 2023). "CA 19-9 and MUC1 showed an intense expression on tumor cells and a lower expression on pancreatic acini and ducts." (PMID 37760554, 2023). "Gatipotuzumab shows enhanced antibody-dependent cell-mediated cytotoxicity (ADCC) and can induce the apoptosis of MUC1-expressing tumor cells." (PMID 37489369, 2023). "While several previous studies have examined the efficacy of MUC1 DNA vaccination in cancer, these studies were mostly conducted in wild-type mice and/or administered exogenous tumor cells." (PMID 36980805, 2023). "Survival of patients with PB tumours showing CK7/MUC1-positive staining and CDX2-negative staining showed a worse prognosis." (PMID 37504367, 2023). "In the present study, tumor cells were observed to be reduced in BM and highly expressed MUC1, SCGB2A2, FN1, BGN, and PEG10." (PMID 37470685, 2023). "MUC1 induces tumor cell plasticity and epigenetic reprogramming by coupling MYC activation with activation of other transcription factors such as STAT3, NF-κB, and E2F." (PMID 36900399, 2023). "Many cycles of patient-derived type I CD4+ T helper cells (Th1) provided by IP together with the cytokines IL-2 and IFN were shown to improve the anti-tumor activity of autologous CD8+ T cells against the tumor-specific glycoform of MUC1." (PMID 37190310, 2023). "MUC1 glycoprotein is overexpressed on the tumor cells, so MUC1 Apt was used to specifically deliver drug-loaded exosomes to cancer cells." (PMID 37009014, 2023). "Recent studies suggest that MUC1 plays a role in modulating cancer cell metabolism, but its role in regulating immunoflogosis in the tumor microenvironment remains poorly understood." (PMID 36902242, 2023). "Studies have shown dual-targeting CAR-T cells MUC1 and ErbB2 were effective in killing MUC1+ and ErbB+ tumour cells, while sparing cells expressing only one of these antigens." (PMID 39935547, 2023). "Analysis of scRNA-seq datasets has demonstrated that MUC1 is widely expressed in TNBC tumor cell populations." (PMID 36445328, 2023). "It has, however, been applied to the investigation of the activation of MUC-1 specific T cells following vaccination with a MUC-1 targeted vaccine in non‒tumor bearing mice." (PMID 37741983, 2023). "Previous studies have reported that binding of galectin-3 to TF on the transmembrane mucin protein MUC1 of tumour cells induces tumour cell-cell homotypic aggregation that promotes circulating tumour cell resistance to anoikis in hematogenous dissemination." (PMID 37612278, 2023). "When mice were immunized with MUC1 DNA + BMDCs, tumor incidence, tumor number, and tumor size were significantly reduced." (PMID 36980805, 2023). "PDAC patients have an overexpression of MUC-1 proteins on tumour cells, indicating another credible target for treatment." (PMID 37686543, 2023). "This BsAb can robustly induce cytokines’ (IFN-γ, TNF-α, and IL-2) secretion in T cells and MUC1-expressing tumor cells’ co-culture assay." (PMID 37489369, 2023).